NOTCH1 (notch receptor 1)
Diseases named in the same sentence as NOTCH1 in open-access papers (continued):
Sharing a sentence is not in itself a finding about the gene and the disease.
tumor (continued). "Recently, epithelial NOTCH1 signaling has been shown to induce tumor microenvironment similar to human colorectal cancer subtype 4, and this is associated with an overall poor prognosis for patients." (PMID 34233177, 2021). "Kunnimalaiyaan and colleagues found that the activation of the Notch-1 gene significantly reduces tumour growth in vitro." (PMID 34439335, 2021). "Flow cytometry showed increased levels of Notch1 on the plasma membrane of cells grown in tumor spheres." (PMID 33922104, 2021). "Notch1 expression correlated with the expression of biomarkers of epithelial to mesenchymal transition in tumor specimens and in in-vitro models and with HCC metastasis." (PMID 33804511, 2021). "In this study, in order to explore the fundamental mechanism(s) by which how miR-221/222 influences CSCs properties in NSCLC, we decided to look at Notch1 signaling since Reck functions as a tumor suppressor by suppressing Notch1 shedding and activation." (PMID 33959615, 2021). "While the role of NOTCH in cancer appears to be tissue specific, NOTCH1 generally functions as a tumor suppressor in the epidermis." (PMID 34553848, 2021). "In line with this, the discovery of the catalysis-independent tumor suppressor function of VAV1 buffering NOTCH1 signaling in T cells further hindered the understanding of the role of VAV proteins in cancer." (PMID 34571765, 2021). "Noteworthy, tumor secreted Gal3 was shown to increase Jagged1 half-life at endothelial cell surface, promoting Notch1/Jagged1 signaling." (PMID 34222228, 2021). "Tumor cells exhibit Notch signaling over-expression, high Notch-1, and Notch-2 levels, while a poor expression of Notch signaling related factors is exhibited by the normal pancreas." (PMID 33670230, 2021). "In vivo mouse models have further shown that deletion of NOTCH1 forcefully decreased mouse xenograft tumor formation." (PMID 33430387, 2021). "One of the critical tasks of HES1, which has been mentioned in various studies, is to cooperate in the development of tumor angiogenesis under the control of Notch1 and inhibit PTEN function." (PMID 36643842, 2021). "In our study, NOTCH1 mutations were found in 43.8% of BCC lesions and were mainly inactivating alterations, which support the tumour-suppressor role of NOTCH1 in BCC tumorigenesis." (PMID 34168209, 2021). "The human SOJ-6 pancreatic tumor cell-derived exosomes were shown to induce (glyco)protein ligand-independent apoptosis and inhibit the Notch-1 pathway in differentiated carcinoma cells, which indirectly favors the growth of undifferentiated tumor cells." (PMID 34957539, 2021). "With this purpose, we evaluated the proportion of cases of each tumor subsite carrying potential driver mutations and/or deep deletions in AJUBA, FAT1 and NOTCH1 in TCGA datasets." (PMID 34208581, 2021). "In summary, this study revealed that circSLC30A7 is an essential tumor suppressor that inhibits HCC tumorigenesis through the miR-767-5p/FBXW7/NOTCH1 axis." (PMID 34675978, 2021). "In vivo experiments confirmed that decreased lncRNA00673 significantly inhibited tumor formation ability of HCC cells through Notch1 and Notch3 down-regulation." (PMID 33804511, 2021). "Four Notch receptors have been associated with tumor growth (Notch1, Notch2, and Notch3), CSC regulation (Notch1, Notch2, Notch4), tumor invasion and metastasis (Notch1, Notch2, Notch3, Notch4), angiogenesis (Notch3), and drug resistance (Notch1 and Notch3)." (PMID 34207383, 2021). "Notch1 signaling has been reported as a cancer promoting pathway in HCC through enhancing tumor cell proliferation, migration, invasion and EMT transformation." (PMID 33767587, 2021). "Accordingly, lower levels of Notch-1/2 in murine tumor-infiltrating CD8 T cells have been reported after GSIs treatment and correlate with reduced tumor control." (PMID 33804511, 2021).
tumor (continued). "We also evaluated the prognostic role of the mutational status of NOTCH1/FBXW7 genes, both including all the patients with available tumor tissue for the genetic analyses and only stage I–III patients." (PMID 34573936, 2021). "NF-κB and MMPs are involved in tumor cell invasion and tumor angiogenesis, inactivated by Notch1 inhibition." (PMID 36643842, 2021). "Inhibition of the Jagged1/Notch1 pathway significantly abolished MSC-induced tumor growth in vitro and in vivo." (PMID 34001269, 2021). "Tumor DNA analysis identified (a) a stop codon leading to loss of function of protein NOTCH1 (p.Q290*) and (b) a genomic amplification of KRAS, which results in overexpression of KRAS protein, activation of KRAS-MAPK pathway, and tumor progression." (PMID 33466719, 2021). "The population of the perivascular niche and resistance in it depend on proficient NOTCH1 expression, whilst NOTCH1 downregulation induces resistant multicellular networks by tumor microtubes extension." (PMID 34445646, 2021). "Although Notch1 can act as an oncogene as well as a tumor suppressor depending on the cellular context, its overexpression clearly associates with poor survival in TNBC." (PMID 34889737, 2021). "In pancreatic ductal adenocarcinoma, NE activates the Notch 1 pathway, enhances the activity and invasion of tumor cells and inhibits the apoptosis of tumor cells." (PMID 34988010, 2021). "BC clinical symptom is accompanied by the high expression of the Notch-1, Notch-3, and Notch-4 pathways, and Notch-2 has been considered to be a tumor suppressor in previous research." (PMID 34135756, 2021). "WNT signaling activation in HN tumor subsites has been associated with genetic alterations in AJUBA, FAT1 and NOTCH1." (PMID 34208581, 2021). "In order to further confirm the suppression of EERAC on downstream proteins of notch signaling pathway, we measured the expression of c-Myc, Jagged1, and Notch1 in the tumor tissues, and similar findings were achieved." (PMID 33403022, 2021). "JAG1 expressed on endothelial cells in the tumour microenvironment activates Notch1 in adjacent BCSCs, resulting in ZEB1 induction and increased stemness." (PMID 34295896, 2021). "Notch1 is a cell surface receptor that plays a pivotal role in supporting tumor cell stemness, EMT, and metastasis." (PMID 34922602, 2021). "Numerous articles have examined the promoting or limiting impact of Notch1 and Notch2 on cell lines, tumor xenografts, animal models, and human tumor specimens." (PMID 36643842, 2021). "We also confirmed that inhibition of the Jagged1/Notch1 pathway significantly abolished MSC-induced tumor growth in vitro and in vivo." (PMID 34001269, 2021). "CSCEXs contain multiple stemness marker proteins, such as CD44v6 and Notch1, which generate transient or dynamic tumor heterogeneity in the tumor microenvironment compared to non-cancer exosomes." (PMID 34062950, 2021). "It has been shown that inhibitors blocking the histone-modulating functions of KMT2A, and related genes potently inhibit tumour cell proliferation in glioma cells, a partly by DNA methylation of NOTCH1 and NOTCH3 genomic locus." (PMID 34944837, 2021). "We also detected NOTCH1-IC expression in xenograft tumor tissues by IHC, which revealed downregulated NOTCH1-IC expression in the sh-APOL1#1 group." (PMID 34341330, 2021). "An overexpression of Notch1 and Notch4 can also be found in iCC and eCC, correlating with tumor aggressiveness." (PMID 33498866, 2021). "NOTCH1 knockout induces epidermal hyperplasia, disrupts differentiation, and promotes tumor formation upon chemical induction." (PMID 34553848, 2021). "By inhibiting the expression of SOX2 in lung cancer, the expression of Wnt1/2, Notch1 and c-myc genes can be down-regulated and tumor cell apoptosis can be induced." (PMID 34135756, 2021). "The activation of Notch-1, which prevents the growth of tumor cells, is shown to be determined by resveratrol." (PMID 34500758, 2021).
tumor (continued). "For PDAC, the expression of ADAM17 (p = 0.008, IHC-score 3.43 vs. 1.73), CD44 (p = 0.012, IHC-score 3.64 vs. 2.27), Notch1 (p = 0.012, IHC-score 2.21 vs. 0.64), and Notch4 (p = 0.008, IHC-score 2.86 vs. 0.91) was significantly higher in the tumor tissue." (PMID 33498866, 2021). "Meanwhile, we detected the levels of c-Myc, Jagged1, and Notch1 in the tumor tissues by IHC staining." (PMID 33403022, 2021). "In contrast, knockdown of NOTCH1 expression led to the reverse effects—impaired spheroid formation, indicating NOTCH1 as a central stimulator and regulator of (tumour) cell stemness." (PMID 34944837, 2021). "Although copy number analysis was inconclusive, elevated NOTCH1 protein in the tumor specimen was established by immunohistochemistry." (PMID 33733072, 2021). "We found significant associations between tumor mRNA expression of IL2RB and NOTCH1 genes and gender and between tumor mRNA expression of IL2RA and MAP2K1 genes and age." (PMID 33672900, 2021). "miR-29, miR-15a, and miR-16 target and repress the translation of tumor-suppressor and cell cycle proteins, including NOTCH1, BCL2, and cyclin." (PMID 34064804, 2021). "PF-3084014 and DAPT enhance the anti-tumor effects of ADT in PCa reversing enzalutamide resistance in CRPC models by decreasing Notch1 activity." (PMID 33791203, 2021). "Maes and colleagues showed that chloroquine can also increase endogenous Notch1 signaling in endothelial cells, inducing tumor vessel normalization in tumors." (PMID 34572582, 2021). "In this case, Notch exerts tumor suppressor activities, especially the NOTCH1 and NOTCH2 receptors, and functional Notch-mediators including RBPJ." (PMID 33430387, 2021). "Among these signaling pathways, Notch1/Hes1 which plays a crucial role in tumor development can be activated by EIF5A2." (PMID 33726845, 2021). "For instance, high levels of Notch1 have been correlated with tumor progression, unfavorable survival and disease recurrence in patients with malignancies of the breast." (PMID 34680255, 2021). "In CSC enriched glioma, exogenous miR-10b exposure led to suppression of NOTCH1, thus diminishing the invasiveness, angiogenesis and tumor growth in the brain, and significantly prolonging the survival of tumor-bearing mice." (PMID 34959397, 2021). "In particular, Notch1 knockdown depleted perivascular niche pool and at the same time stimulated the formation of tumor microtubules responsible for the formation of communicating network inside the tumor." (PMID 34680255, 2021). "NOTCH1 mRNA was significantly upregulated in AK compared with that in the normal skin (in two datasets), suggesting tumor promoter function, which contrasts with previous findings in cSCC where it is inactivated early in cSCC pathogenesis." (PMID 33482222, 2021). "It has been reported that miR-139-5p targets Notch-1 and regulates its signal transduction to exert tumour suppressive effect in CRC." (PMID 34733591, 2021). "In this study, we analysed the GSE108989 data set of T cells and found that NOTCH1 and FBXW7 mutations in CRC patients were associated with higher expression levels of PDCD1, CTLA4 and GZMB of tumour‐infiltrating CD8+ T cells." (PMID 32924269, 2020). "Intriguingly, depletion of Notch1 in cancer cells led to a decrease in Treg cells detected in the TME, suggesting the immune-suppressive aspects of tumor-associated Notch1 receptor." (PMID 33585446, 2020). "The potent PI3K inhibitor PX-886 significantly reduced tumor growth in two NOTCH1 mutant HNSCC patient-derived xenograft models." (PMID 33322834, 2020). "Notch-1 has been shown to have both tumor suppressive and tumorigenic function in different contexts and the level of expression has also been suggested to influence the degree of malignancy in a dose-dependent manner." (PMID 32197359, 2020).
tumor (continued). "Most of the cells in cluster 2 were from tumours of P0909 (NOTCH1 and FBXW7 mutations) and P1012 (NOTCH1 mutation), and most of the cells in cluster 4 were from tumour of P0701 (two types of FBXW7 mutations)." (PMID 32924269, 2020). "Consistently, we found that tumours with Notch1 activation exhibited faster progression than did non-Notch1-driven tumours." (PMID 32591500, 2020). "Notch receptor 1 (Notch1), a type 1 trans-membrane receptor, is a key regulator of tumor angiogenesis and metastasis." (PMID 33194731, 2020). "At the same time, increased NOTCH1 activity in these cells ensures elevated expression of a battery of CAF effector genes with established tumor-promoting functions." (PMID 33046701, 2020). "Better anti-Notch directed therapies, specifically directed against the tumor promoting Notch receptor 1 signaling framework, and biomarkers predicting response to such therapy are of highest clinical need." (PMID 33004830, 2020). "It is important to highlight that previous studies regarding the participation of NOTCH1 in tumor development of cHL have been carried out in animal models and/or cancer cell lines." (PMID 32604737, 2020). "Overall, our data demonstrated that p65-induced Notch1 activation was required for the contact-dependent induction of CXCL8 in the tumor-stroma-inflammation network, promoting malignancy-related function in TNBC cells." (PMID 32605277, 2020). "Activation of the Notch-1 signal plays an important role in the self-renewal, proliferation, and apoptosis of tumor cells." (PMID 33344242, 2020). "The aim was to analyse the tumor expression of Notch1, Hes1, Ascl1, and DLL3in Small-Cell Lung Cancer (SCLC) and each such biomarker’s potentialassociation with clinical characteristics and prognosis afterplatinum-doublet chemotherapy (PDCT)." (PMID 33104707, 2020). "Reduction in expression levels of Notch1 and its targets in thymic pre-T cells of tumor-bearing mice is mediated by IL-10 produced by thymic epithelial cells (TECs)." (PMID 32922403, 2020). "PDGF-D can promote tumor angiogenesis of colorectal cancer by activating Notch1/Twist1 signaling and recruiting macrophages to tumor tissues." (PMID 32993787, 2020). "On one hand, NRARP has a ‘tumor suppressor’-like role in T-ALL cells with high levels of NICD by inhibiting Notch1 signaling." (PMID 31586130, 2020). "Using the secretase inhibitors DAPT and DBZ, affecting primarily Notch1, only led to a partial abrogation of mammosphere-forming units and tumor formation." (PMID 32796631, 2020). "We were therefore able to analyze the expression of NANOG, SOX2, OCT4, AGR2, KLF4, and NOTCH1 in only 11 tumor samples and corresponding TANT (22 FFPE tissue samples)." (PMID 32733958, 2020). "Gene set enrichment analysis (GSEA) demonstrated that genes upregulated in the EMT process were highly expressed in Notch1-driven tumours." (PMID 32591500, 2020). "Further research demonstrated that Notch1 and Notch4 immunoreactivity significantly correlated with tumor grade and Ki67 expression in triple-negative breast tumors." (PMID 33003540, 2020). "We also showed that CAFs carrying elevated Notch1 activity significantly inhibited tumor growth and invasion, whereas those with a null Notch1 activity promoted tumor invasion." (PMID 33109684, 2020). "These experiments demonstrated the tumor-suppressive capacity of NOTCH1 signaling in naturally occurring NOTCH1 mutant cell lines." (PMID 33322834, 2020).
tumor (continued). "Although the role of Notch1 in cancer formation has been well established, it is somewhat surprising that it can act as an oncogene or a tumour suppressor in different contexts." (PMID 32591500, 2020). "We further showed that the elevation of LNX1 and Notch1 results in an increase in the tumor stem cell population, a subpopulation of cells thought to help propagate a more aggressive tumor." (PMID 33255632, 2020). "Among the different modulators of NOTCH1 signaling, miRNAs have been shown to play an important role in tumor progression, suggesting the possibility of combining NOTCH1 inhibition with miRNA-based therapy." (PMID 32708470, 2020). "It has been shown that in BCC tumor regions, the expression of NOTCH1, DLL1 and JAG1 is lowered in comparison to physiological healthy regions, the basal layer." (PMID 32796631, 2020). "A large number of studies have revealed that Notch1 signaling pathway exerts great influence in tumor development." (PMID 33598419, 2020). "The results showed that combination of DOX with GSI significantly decreased the Notch-1 expression in the tumor tissues when compared with DOX or GSI alone." (PMID 32586404, 2020). "HD and PEST domain missense mutations are prevalent in T-ALL, where they lead to increased NOTCH1 signaling, driving tumor formation." (PMID 33322834, 2020). "CQ administration leads to NOTCH1 accumulation in endothelial cell endosomes, stimulating the downstream signalling that leads to tumour vessel normalization, and resulting in reduced tumour invasion and metastasis." (PMID 32715647, 2020). "Structural characterization of NOTCH1 mutations in HNSCC demonstrates that most are predicted to cause loss of function, in agreement with NOTCH1’s role as a tumor suppressor in this cancer." (PMID 33322834, 2020). "Analysis of RT-qPCR data revealed significantly higher expression levels of NOTCH-1 mRNA in NSCLC tissues compared to non-tumor tissues (p < 0.05)." (PMID 32349744, 2020). "Dysregulation of these multi-cellular communication networks can contribute to chronic liver diseases and tumorigenesis as illustrated for Notch1 signaling and its impact on tumor cell dissemination." (PMID 33097058, 2020). "The RNA-seq data obtained in HCC-1599 and MB-157 cells exposed to ATRA, DAPT and ATRA+DAPT provide clues as to the gene networks and pathways participating in the NOTCH1-dependent anti-tumor action of the two compounds alone or in combination." (PMID 33081033, 2020). "In contrast, genes downregulated during EMT revealed low levels of expression in Notch1-driven tumours." (PMID 32591500, 2020). "In parallel, Notch1 induced accumulation of p65 in the nucleus, elevated IκBα degradation and up-regulated the formation of NF-κB-DNA complexes, suggesting that Notch1 induced tumor-promoting activities by activating NF-κB." (PMID 32605277, 2020). "In vivo imaging over a 2 weeks period showed reduced time-dependent expansion of the fluorescently labeled SCC13 cells in the presence of CAFs with silenced NOTCH1 versus controls and a smaller tumor volume at the time of collection." (PMID 33046701, 2020). "Several studies have indicated that miR-34a modulates the migration and invasion of tumor cells by down-regulating hepatocyte nuclear factor 4 gamma (HNF4γ) and Notch1." (PMID 33221743, 2020). "We were able to demonstrate that Notch1 regulation contributes to the tumorigenic activity of G9a, which suggests a new function of G9a in controlling tumor growth." (PMID 32015216, 2020). "NOTCH1 can function as either a tumor promoter or suppressor largely depending on the cellular context." (PMID 33322834, 2020). "The tumour-promoting effect of Notch1 inactivation in the epithelia of the skin, oral cavity and oesophagus is well established, and our data suggest that this is mediated, at least in part, by triggering inflammation." (PMID 33168804, 2020).